TMCO6 (transmembrane and coiled-coil domains 6)
Synonyms: PRO1580; FLJ39769
Tractability: Antibody: UniProt predicts a signal peptide or a membrane-spanning region. PROTAC: ubiquitination databases record sites on it.
Gene: Protein-coding gene on chromosome 5 (140,639,427 to 140,645,801, forward strand). Ensembl gene ENSG00000113119.
Subcellular location: Membrane
Subcellular location (Human Protein Atlas): Mitochondria; Nucleoplasm
Gene Ontology:
Molecular function: protein binding; nuclear import signal receptor activity
Biological process: protein import into nucleus
Cellular component: membrane
Genetic constraint (gnomAD): Loss-of-function variants: 47 observed, 62.91 expected, observed/expected ratio (o/e) 0.75, 90% interval 0.59 to 0.95. The upper end of that interval is the gene's LOEUF score, 0.95, which puts it in group 4 of 6, group 1 being the genes least tolerant of losing a copy. Missense variants: 557 observed, 619.64 expected, observed/expected ratio (o/e) 0.9, 90% interval 0.84 to 0.96. Synonymous variants: 261 observed, 258.95 expected, observed/expected ratio (o/e) 1.01, 90% interval 0.91 to 1.12.
Homologues: Orthologues: chimpanzee TMCO6 (99% identical), macaque TMCO6 (98% identical), pig TMCO6 (88% identical), dog TMCO6 (87% identical), rabbit TMCO6 (87% identical), guinea pig TMCO6 (86% identical), rat Tmco6 (84% identical), mouse Tmco6 (83% identical), tropical clawed frog tmco6 (46% identical), zebrafish tmco6 (45% identical), Drosophila melanogaster CG15443 (17% identical).
Diseases named in the same sentence as TMCO6 in open-access papers:
TMCO6 is named in the same sentence as 7 diseases in open-access papers, as found by Europe PMC text mining. Sharing a sentence is not in itself a finding about the gene and the disease. The quoted sentences say what the papers report.
colorectal cancer (1 paper, 2021). A primary or metastatic malignant neoplasm that affects the colon or rectum. "Moreover, the role of DENND6B, NCOA7and TMCO6 in cancer is largely unknown, our results indicated their important role in colorectal cancer; further studies are expected to reveal their biological function." (PMID 34035992, 2021).
hepatocellular carcinoma (1 paper, 2026). A malignant tumor that arises from hepatocytes. "In addition, in hepatocellular carcinoma, TMCO6 interacts with NET-DNA and suppressed T cell receptor signaling, thereby impairing anti-tumor immunity and promoting cancer progression." (PMID 41550766, 2026).
periodontal disease (1 paper, 2019). "Of these, WHAMM and TMCO6 were identified as likely signals of genomic regulation in periodontal disease, due to a significant association between phenotype-associated methylation and gene expression levels at these genes." (PMID 30760334, 2019). "Both findings suggest that WHAMM and TMCO6 are strong candidates to shed light on epigenetic modifications over the course of periodontal disease." (PMID 30760334, 2019).
cancer (2 papers, 2021 to 2026). A tumor composed of atypical neoplastic, often pleomorphic cells that invade other tissues. "TMCO6 is associated with poor prognosis in several cancers including CRC." (PMID 41550766, 2026).
TMCO6 also shares sentences with these, for which no sentence is quoted: chronic periodontitis (1 paper); Gingival bleeding (1); tumor (1).